CEACAM19 (CEA cell adhesion molecule 19)
Synonyms: CEAL1; CEACM19
Tractability: Antibody: UniProt predicts a signal peptide or a membrane-spanning region.
Gene: Protein-coding gene on chromosome 19 (44,662,278 to 44,684,360, forward strand). Ensembl gene ENSG00000186567.
Subcellular location: Membrane
Subcellular location (Human Protein Atlas): Mitochondria; Nucleoli; Nucleoplasm
Gene Ontology:
Molecular function: protein binding
Biological process: heterophilic cell-cell adhesion; homophilic cell-cell adhesion
Cellular component: plasma membrane; membrane
Genetic constraint (gnomAD): Loss-of-function variants: 33 observed, 29.5 expected, observed/expected ratio (o/e) 1.12, 90% interval 0.85 to 1.5. The upper end of that interval is the gene's LOEUF score, 1.5, which puts it in group 6 of 6, group 1 being the genes least tolerant of losing a copy. Missense variants: 311 observed, 329.92 expected, observed/expected ratio (o/e) 0.94, 90% interval 0.86 to 1.03. Synonymous variants: 129 observed, 132.82 expected, observed/expected ratio (o/e) 0.97, 90% interval 0.84 to 1.12.
Homologues: Orthologues: macaque CEACAM19 (96% identical), chimpanzee CEACAM19 (88% identical), pig CEACAM19 (68% identical), rat Ceacam19 (62% identical), mouse Ceacam19 (60% identical), dog CEACAM19 (53% identical). Paralogues in human: CEACAM5 (20% identical), CEACAM1 (19% identical), HEPACAM2 (16% identical), PSG3 (16% identical), CEACAM8 (16% identical), PSG4 (16% identical), PSG6 (16% identical), PSG9 (16% identical), CEACAM16 (15% identical), PSG7 (15% identical), CEACAM6 (15% identical), PSG5 (15% identical), and 12 more.
Diseases named in the same sentence as CEACAM19 in open-access papers:
CEACAM19 is named in the same sentence as 7 diseases in open-access papers, as found by Europe PMC text mining. Sharing a sentence is not in itself a finding about the gene and the disease. The quoted sentences say what the papers report.
breast carcinoma (3 papers, 2018 to 2021). "It has also been demonstrated that CEACAM5, CEACAM6, and CEACAM19 are overexpressed in breast cancer and are associated with enhanced tumor invasiveness and metastasis." (PMID 34447411, 2021). "CEACAM19 gene located in chromosome 19, a previous study showed high expression of CEACAM19 for patients with breast cancer; CLPTM1 has been shown to increase the risk of lung cancer and melanoma." (PMID 30666269, 2018). "CEACAM19 (CEA cell adhesion molecule 19), DIO3OS (DIO3 opposite strand upstream RNA), and PCAT6 (prostate cancer associated transcript 6) were verified as associated with the prognosis of different cancers, including gastric cancer, breast cancer, liver cancer, and lung cancer." (PMID 33043022, 2020).
gastric cancer (2 papers, 2020 to 2022). A primary or metastatic malignant neoplasm involving the stomach. "Some of these genes are already related to cancer, namely, high expression of CEACAM19 in tumor breast samples and gastric cancer tissues." (PMID 36010616, 2022).
cancer (5 papers, 2014 to 2025). A tumor composed of atypical neoplastic, often pleomorphic cells that invade other tissues. "To further validate these findings, we analyzed paired tissue samples from TCGA and IHC images from the Human Protein Atlas (HPA), which revealed that CEACAM19 expression was significantly higher in cancer tissues compared to normal controls." (PMID 40842663, 2025). "In this study, an ITAM was also detected in the cytoplasmic tail of CEACAM19, which is overexpressed in several types of cancer." (PMID 24858421, 2014). "In the Cancer group, 4429 mRNAs were up regulated and 2937 mRNAs were down regulated, and among these, CEACAM 3, 4, 5, 6 and 20 were verified up regulated and CEACAM19 was down regulated." (PMID 34221964, 2021).
CEACAM19 also shares sentences with these, for which no sentence is quoted: tumor (3 papers); lung carcinoma (2); liver cancer (1); melanoma (1).